ITPR1 (inositol 1,4,5-trisphosphate receptor type 1)
Diseases named in the same sentence as ITPR1 in open-access papers (continued):
Sharing a sentence is not in itself a finding about the gene and the disease.
cancer (continued). "EGOT can directly bind to the cis-acting element in ITPR1 pre-mRNA, resulting in the recruitment of the SF hnRNPH1 to promote hnRNPH1-mediated AS, contributing to the expression of the ITPR1 protein, which sensitizes cells to paclitaxel cytotoxicity in cancer therapy." (PMID 33407694, 2021). "Moreover, the lncRNA EGOT participates in the AS of ITPR1 pre-mRNA, sensitizing cancer cells to paclitaxel treatment." (PMID 33407694, 2021). "Moreover, the stability of pre-ITPR1 mRNA was increased in EGOT-overexpressing cancer cells compared with that in control cells, as shown in the transcriptional inhibition experiments." (PMID 30999914, 2019). "Thus, we propose that hnRNPH1 mediates pre-ITPR1 splicing in human cancer by binding these GGGA/C/G motifs." (PMID 30999914, 2019). "Moreover, the presence of malignant tumours in two of our patients as well as the expression of ITPR1 within the tumour in one of them suggests a paraneoplastic aetiology of ITPR1 at least in a subset of patients." (PMID 27776522, 2016). "Even though four (PIK3C2A, JUN, FNBP1, ITPR1) of our peripheral biomarkers have been implicated in cancer pathophysiology, none of the PBMC biomarkers were differentially expressed between tumor types (among all subjects, or within cases or controls alone)." (PMID 21884629, 2011). "From the results above, we hypothesize that the oncogenic effect of ITPR3 is partly attributed to the inhibition of ITPR1 and that the ratio of ITPR3/ITPR1 may determine the destiny of cancer cells which is consistent with the conjectures in the previous research." (PMID 33573671, 2021). "Collectively, these data suggest that EGOT may induce ITPR1 expression in human cancer." (PMID 30999914, 2019). "Emerging evidence has indicated that ITPR1, ITPR2, and ITPR3 were universally dysregulated in many cancers." (PMID 35580861, 2022). "CAPN2, ITPR1, PPP3CA, and PRKCA were enriched in calcium-induced T lymphocyte apoptosis pathway, and not reported on tumor-host immunological interactions, but those proteins were repeatedly reported relevant to human cancers." (PMID 31258820, 2019). "By fractionated nuclear and cytoplasmic RNA analysis and RNA fluorescence in situ hybridization (RNA-FISH) examination in four cancer cell lines, we found that EGOT is mainly expressed in the nucleus, suggesting that EGOT exerts its regulatory function for ITPR1 at the transcriptional level." (PMID 30999914, 2019). "Moreover, nutrient starvation failed to induce autophagy when ITPR1 was knocked down in cancer cells, as shown by confocal microscopy examination 48 h after mRFP-GFP-LC3 adenovirus vector transfection." (PMID 30999914, 2019).
tumor (39 papers, 2011 to 2026). "ITPR1 is not only associated with neurological syndromes but also takes part in tumor carcinogenesis." (PMID 35580861, 2022). "In a substantial proportion of patients ITPR1-IgG/anti-Sj was found to be associated with tumours, some of which were demonstrated to express ITPR1." (PMID 35907972, 2022). "Here, we provide a review of the available literature on ITPR1-IgG/anti-Sj, covering clinical and paraclinical presentation, tumour association, serological findings, and immunopathogenesis." (PMID 35907972, 2022). "ITPR1 was negatively correlated with tumor size, tumor lymph node metastasis (TNM) staging, lymph node metastasis (LNM), estrogen receptor (ER), progesterone receptor (PR) and HER2 status (P < 0.05)." (PMID 35313846, 2022). "The results of this study clarify the mechanism of ITPR1 gene and its prognostic significance in treatment, and provide the potential relationship and mechanism of ITPR1 and tumor immune interaction." (PMID 35313846, 2022). "TIMER analysis found that after the correlation adjustment of tumor purity, the results showed that ITPR1 in BRCA-Basal was closely related to the immune markers of most immune cells." (PMID 35313846, 2022). "Of note, immunopathology revealed substantial ITPR1 expression in the tumour and the metastatic lymph nodes." (PMID 35907972, 2022). "Next, we used the GEPIA dataset and the TIMER dataset to compare the expression of ITPR1 between tumor tissues and normal tissues." (PMID 35313846, 2022). "Taken together, our data elucidated that SLC26A4‐AS1 promoted autophagy and suppressed PTC tumour growth through ETS1‐mediated ITPR1 regulation." (PMID 34378314, 2021). "As Western blot analysis confirmed the efficiency of transfection, the oe‐ITPR1‐treated cells were subcutaneously injected into nude mice and the weight and size of xenografted tumours were measured." (PMID 34378314, 2021). "Due to this association with tumors, we strongly recommend a thorough search for neoplasia, whenever anti-ITPR1 antibodies are detected." (PMID 34635185, 2021). "In the current study, in the presence of overexpression of ITPR1, autophagy was enhanced, accompanied by decreased tumour volume and greater prognosis." (PMID 34378314, 2021). "The results showed a significant decrease in tumor volume in mice engrafted with ITPR1-defective Renca cells as compared to control cells." (PMID 26910842, 2016). "Global gene expression profiling identified the inositol 1,4,5-triphosphate receptor, type I (ITPR1) as a new HIF-2α downstream target gene involved in the regulation of NK-mediated anti-tumor immune response." (PMID 26910842, 2016). "Consistent with the in vitro observations, the relevance of HIF-2α/ITPR1/autophagy pathway on NK-dependent anti-tumor immune response using Renca murine RCC was investigated." (PMID 26910842, 2016). "Tumour screening is essential in patients presenting with ITPR1-IgG/anti-Sj." (PMID 35907972, 2022). "The results showed ITPR1 had lower expression in most tumor tissues than in normal tissues." (PMID 35313846, 2022). "In addition, the TIMER database was used to analyze the correlation between ITPR1 and tumor infiltrating immune cells." (PMID 35313846, 2022). "This study highlights that targeting the autophagy sensor ITPR1 could be an alternative strategy to improve NK-mediated anti-tumor immune response in renal carcinoma." (PMID 26910842, 2016). "ITPR1-IgG serum titres declined following tumour removal, paralleled by clinical stabilization." (PMID 27776522, 2016). "In vivo, ITPR1 targeting significantly enhanced NK-mediated tumour regression." (PMID 27776522, 2016). "Furthermore, by analyzing CCLE data, we found that ITPR1 may impact paclitaxel sensitivity in tumor cells." (PMID 30999914, 2019). "ITPR1 knockdown suppressed GBM cell proliferation and tumor growth while promoting intrinsic apoptosis." (PMID 42193173, 2026).
tumor (continued). "We further treated CRC cells with semaglutide and found that the expression of ITPR1 and ADCY5 was activated, along with inhibition of tumor cell migration." (PMID 39104385, 2024). "IHC staining indicated that ITPR1 and ADCY5 expression were decreased in tumor tissues than normal tissues." (PMID 39104385, 2024). "We observed significantly higher expression of METTL16, ITPR1, CAPN2, ITGA3, RAC1, ITGA6, and CHMP28 in tumor samples (P<0.05)." (PMID 39434688, 2024). "ITPR1‐induced autophagy was also reported in other tumours, including PTC where ITPR1 was identified as a differential expressed gene correlated with prognosis." (PMID 34378314, 2021). "For some antigens like ATP1A3, ITPR1, or ROCK2 an expression in tumor samples of the respective index patient was observed, pointing to a paraneoplastic autoimmune background." (PMID 30038610, 2018). "Moreover, hypoxia-induced autophagy degrades NK-derived Granzyme B in tumor cells through the autophagy sensor Inositol 1,4,5-Trisphosphate Receptor Type 1 (ITPR1), thus impairing NK-mediated tumor cell degradation." (PMID 35211123, 2022). "As a result, we found that ITPR1, ITPR2, and ITPR3 proteins may interact with tumor-promoting genes, such as PLCB1, PLCB2, PRKCA, and RGS21, which may partially explain its oncogene roles." (PMID 35580861, 2022). "This decrease is presumably due to the improvement of NK-mediated anti-tumor immune response since the regression of ITPR1 defective tumors was no longer observed in NK-depleted mice." (PMID 26910842, 2016). "Similarly, an ITPR1 mutation in TN1 fails to be recovered by the truncal tool, because it appears in only two of the four primary tumor samples that were included, and is also absent from one metastatic sample." (PMID 33771218, 2021). "Anti-Sj/ITPR1-IgG titres were extraordinarily high both in the IHC assay (up to 1:15,000) and in the CBA (up to >1:1000) during acute disease in patient 1; after removal of the tumour (and thus of the ectopically presented antigen), CBA titres declined to 1:320 and later 1:100." (PMID 27776522, 2016). "However, the tumor did not express ITPR1, GFAPα or MOG antigen (supplement)." (PMID 34635185, 2021). "Supposing that ITPR1 is truly protective of RCC cells, its downregulation in ccRCC organoids after cabozantinib treatment could be indicative of reliance on separate pathways for survival or suggestive that it is not critical for tumor survival." (PMID 40352330, 2025).
neurological disorders (8 papers, 2009 to 2025). "If that is so, ITPR1-IgG/anti-Sj may just be a diagnostic marker, as is the case in other paraneoplastic neurological disorders, and T cell-mediated pathomechanisms may play a more important role." (PMID 35907972, 2022). "Importantly, the expression of genes related to synaptic plasticity and neurological diseases such as Arc, Homer1, and Itpr1 in the TgL group were significantly upregulated compared with the TgW group." (PMID 40420177, 2025).
peripheral neuropathy (5 papers, 2016 to 2025). A disorder affecting the peripheral nervous system. "A few cases with autoimmune cerebellar ataxia and peripheral neuropathy targeting inositol 1,4,5-triphosphate receptor type 1 (ITPR1) have been published." (PMID 34635185, 2021). "The variants CACNA1A c.6692G > A (NM_023035.2), BAG3 c.494C > T (NM_004281.3), and ITPR1 c.6692A > G (NM_001168272.1) did not segregate with the peripheral neuropathy phenotype." (PMID 31852952, 2019).
adenocarcinoma (2 papers, 2016 to 2022). A common cancer characterized by the presence of malignant glandular cells. "ITPR1 has been shown to be expressed in a subset of adenocarcinomas of the lung as demonstrated by Western blot and conventional immunohistochemistry; by contrast, no or only low levels of ITPR1 protein expression have been reported in normal lung tissue." (PMID 27776522, 2016).
brain disorder (2 papers, 2018 to 2024). A disease affecting the brain or part of the brain. "As enhancer variations are being increasingly recognized as a cause of brain disorders, screening the enhancers of ATXN1, ATXN3, TBP and ITPR1 for variations other than CNVs and identifying and screening enhancers of other SCA genes might elucidate the genetic cause in undiagnosed patients." (PMID 39456985, 2024).
bacterial infection (1 paper, 2008).
cardiovascular disease (1 paper, 2021). "Calnexin is an ER chaperone that has been implicated in cardiomyocyte viability and in ER stress, a prominent clinical feature of cardiovascular disease, while ITPR1 mediates the influx and release of intracellular Ca2+ and is regulated by the palmitoylation cascade of ZDHHC16/ZDHHC6." (PMID 34252155, 2021).
neurodevelopmental disorder (1 paper, 2021). A behavioral and cognitive disorder with onset during the developmental period that involves impaired or aberrant development of intellectual, motor, or social functions. "The pathomechanism explaining the disease mechanism remains unknown, however several others genes of the inositol phosphatase metabolism (e.g., INPP5K, FIG4, INPP5E, ITPR1) are correlated with phenotypes of neurodevelopmental disorders." (PMID 33168985, 2021).
vasculopathies (1 paper, 2018). "MRVI1 is a functional partner of other genes (ITPR1, PRKG1 and GUCY1A3), differently related to MMS and other vasculopathies, but together involved in response to NO." (PMID 30001348, 2018).
ITPR1 also shares sentences with these, for which no sentence is quoted: cerebellar ataxia (24 papers); atherosclerosis (5); ovarian carcinoma (5); type 2 diabetes (5); colon cancer (4); colorectal cancer (4); glioblastoma (4); Insulin resistance (4); atrial fibrillation (3); cardiac hypertrophy (3); clear cell renal cell carcinoma (3); Cognitive impairment (3); dentatorubral-pallidoluysian atrophy (3); diabetes (3); infection (3); melanoma (3); myocardial ischemia (3); acute pancreatitis (2); adenocarcinoma of the lung (2); Adult onset (2); anhidrosis (2); Arrhythmia (2); autoimmune encephalitis (2); bipolar disorder (2); Breast invasive carcinoma (2); cardiomyopathy (2); COVID-19 (2); Dyskinesia (2); Encephalopathy (2); hereditary spastic paraplegia (2).
A further 94 diseases each share a sentence with ITPR1 in 2 papers or fewer.